MIR500A (microRNA 500a)
Synonyms: hsa-mir-500; MIR500; MIRN500; hsa-mir-500a; mir-500a
Gene: MicroRNA gene on chromosome X (50,008,431 to 50,008,514, forward strand). Ensembl gene ENSG00000207785.
Gene Ontology:
Biological process: miRNA-mediated post-transcriptional gene silencing
Cellular component: RISC complex
Homologues: Orthologues: chimpanzee ptr-mir-500-1 (99% identical), macaque mml-mir-500a (99% identical), pig ssc-mir-500 (93% identical), rabbit MIR500A (69% identical). Paralogues in human: MIR502 (90% identical), MIR501 (89% identical), MIR500B (85% identical).